R3HDM1 (R3H domain containing 1)
Synonyms: KIAA0029; R3HDM
Tractability: PROTAC: ubiquitination databases record sites on it; its protein half-life has been measured.
Gene: Protein-coding gene on chromosome 2 (135,531,448 to 135,725,314, forward strand). Ensembl gene ENSG00000048991.
Subcellular location (Human Protein Atlas): Cytosol; Nucleoplasm
Gene Ontology:
Molecular function: RNA binding; nucleic acid binding
Genetic constraint (gnomAD): Loss-of-function variants: 40 observed, 136.27 expected, observed/expected ratio (o/e) 0.29, 90% interval 0.23 to 0.38. The upper end of that interval is the gene's LOEUF score, 0.38, which puts it in group 1 of 6, group 1 being the genes least tolerant of losing a copy. Missense variants: 1,173 observed, 1,401.8 expected, observed/expected ratio (o/e) 0.84, 90% interval 0.8 to 0.88. Synonymous variants: 432 observed, 484.99 expected, observed/expected ratio (o/e) 0.89, 90% interval 0.82 to 0.96.
Homologues: Orthologues: macaque R3HDM1 (99% identical), chimpanzee R3HDM1 (96% identical), dog R3HDM1 (93% identical), guinea pig R3HDM1 (93% identical), pig R3HDM1 (91% identical), mouse R3hdm1 (91% identical), rabbit R3HDM1 (91% identical), rat R3hdm1 (91% identical), tropical clawed frog r3hdm1 (69% identical), zebrafish r3hdm1 (37% identical). Paralogues in human: R3HDM2 (47% identical), ARPP21 (39% identical).
Diseases named in the same sentence as R3HDM1 in open-access papers:
R3HDM1 is named in the same sentence as 15 diseases in open-access papers, as found by Europe PMC text mining. Sharing a sentence is not in itself a finding about the gene and the disease. The quoted sentences say what the papers report.
Adrenocortical carcinoma (1 paper, 2024). "The high SNV Neoantigens score of R3HDM1 expression is positively correlated with Adrenocortical carcinoma (ACC), Bladder Urothelial Carcinoma (BLCA), BRCA, HNSC, Kidney renal papillary cell carcinoma (KIRP), LUSC, LUAD, Prostate adenocarcinoma (PRAD), and Thymoma (THYM)." (PMID 39376739, 2024).
lung adenocarcinoma (1 paper, 2024). A carcinoma that arises from the lung and is characterized by the presence of malignant glandular epithelial cells. "Multi omics studies have elucidated the dysregulation of R3HDM1 expression in pan cancer, which is a potential diagnostic marker for pan cancer and has been confirmed in lung adenocarcinoma cell lines." (PMID 39376739, 2024). "Cell migration and proliferation experiments were conducted by knocking down the expression of R3HDM1 in two lung adenocarcinoma cell lines using small interfering RNA." (PMID 39376739, 2024). "At last, the normalized RT-qPCR results show substantial variations in R3HDM1 expression levels between normal lung glandular epithelial cells and lung adenocarcinoma cells." (PMID 39376739, 2024). "The differential expression of R3HDM1 was verified in lung adenocarcinoma cell lines and normal lung glandular epithelial cells via RT-qPCR." (PMID 39376739, 2024). "In conclusion, our study highlights the significant role of R3HDM1 in the development and progression of lung adenocarcinoma." (PMID 39376739, 2024). "In vitro cellular experiments were conducted to validate the differential expression of R3HDM1 between lung adenocarcinoma cell lines and normal lung glandular epithelial cells." (PMID 39376739, 2024). "Overall, this study proposes that R3HDM1 expression is a promising biomarker for predicting the prognosis of cancer, especially lung adenocarcinoma, and the efficacy of immunotherapy, demonstrating the rationale for further exploration in the development of anti-tumor therapies." (PMID 39376739, 2024).
lung carcinoma (1 paper, 2024). "It is evident that, except for the testis, thyroid, brain, and kidney, cancer tissues show significantly higher expression of R3HDM1 compared to normal tissues in other organs, with lung cancer tissues still exhibiting significantly higher expression than normal lung tissue." (PMID 39376739, 2024).
melanoma (1 paper, 2024). A malignant, usually aggressive tumor composed of atypical, neoplastic melanocytes. "We found varied predictive performance of R3HDM1 across different datasets, with the best performance observed for Melanoma and good performance for RCC, NSCLC, LGG, and GBM." (PMID 39376739, 2024). "The higher expression of R3HDM1 in the metastatic group in melanoma further indicates its role in tumor metastasis." (PMID 39376739, 2024).
mesothelioma (1 paper, 2024). A usually malignant and aggressive neoplasm of the mesothelium which is often associated with exposure to asbestos. "Additionally, the high MSI scores in Lymphoid Neoplasm Diffuse Large B-cell Lymphoma (DLBC), HNSC, Mesothelioma (MESO), KIRP, LUSC, Thyroid carcinoma (THCA), Rectum adenocarcinoma (READ), Skin Cutaneous Melanoma (SKCM), and STAD are positively correlated with R3HDM1 expression." (PMID 39376739, 2024).
periodontitis (1 paper, 2022). An acute or chronic inflammatory process that affects the tissues that surround and support the teeth. "EPB41L4A-AS1, INSR and R3HDM1 are potential crosstalk genes between periodontitis and COPD." (PMID 35676670, 2022). "EPB41L4A-AS1, INSR and R3HDM1 are potential crosstalk genes between COPD and periodontitis." (PMID 35676670, 2022).
cancer (1 paper, 2024). A tumor composed of atypical neoplastic, often pleomorphic cells that invade other tissues. "High expression of R3HDM1 was identified as a risk factor for the occurrence and progression of tumors, particularly in six types of cancers (ACC, LUAD, MESO, UCEC, THCA, and KIRP)." (PMID 39376739, 2024). "Survival analysis across various cancer types revealed a consistent association of R3HDM1 with multiple survival periods, primarily as a risk factor for various cancers, notably in LUAD." (PMID 39376739, 2024). "Understanding the significance of R3HDM1 in the context of cancer could potentially offer new insights into its diagnostic, prognostic, and immunotherapeutic value across a spectrum of cancer types." (PMID 39376739, 2024). "Additionally, the association between R3HDM1 expression levels and clinical characteristics in different types of cancers was evaluated." (PMID 39376739, 2024). "The study explored the clinical relevance of R3HDM1 in cancer by analyzing its role in cancer survival." (PMID 39376739, 2024). "This study, for the first time, comprehensively elucidated the dysregulated expression of R3HDM1 in pan-cancer using diverse tools, suggesting its potential as a diagnostic biomarker across multiple cancers." (PMID 39376739, 2024). "The result shows that in the high R3HDM1 expression group of almost all cancer types, cell proliferation-related signaling pathways (including MYC, mTORC1, spindle, G2M, and E2F pathways) are significantly enriched." (PMID 39376739, 2024). "This study aims to comprehensively investigate the functional implications of R3HDM1 in cancer development and progression." (PMID 39376739, 2024). "R3HDM1, also known as an RNA-binding protein with an R3H domain, has emerged as a pivotal focus in cancer research." (PMID 39376739, 2024). "In summary, these results strongly indicate that the elevated levels of R3HDM1 are closely associated with increased proliferation, EMT, and immune suppression in human cancers." (PMID 39376739, 2024). "By combining and mining the resources of TCGA and GTEx databases, we obtained the mRNA expression levels of R3HDM1 from a pan-cancer perspective." (PMID 39376739, 2024). "The findings from this study are expected to shed light on how elevated R3HDM1 expression correlates with poor prognosis and altered drug sensitivity in different cancer types." (PMID 39376739, 2024). "From the result, fasudil, imatinib, NU1025, and 4,5-Dianilinophthalimide exhibited significantly lower scores across most cancer types, suggesting their potential to inhibit R3HDM1-mediated oncogenic effects." (PMID 39376739, 2024). "The study also characterized a pan-cancer survival profile and analyzed the differential expression of R3HDM1 in different molecular subtypes." (PMID 39376739, 2024). "To further understand the impact of R3HDM1 on the prognosis of cancer patients, especially LUAD, we conducted Gene Set Enrichment Analysis (GSEA)." (PMID 39376739, 2024). "We found differential expression of R3HDM1 in most types of cancer, and consistent expression patterns across cancer types, with a universal significant upregulation." (PMID 39376739, 2024). "Firstly, we examined the differentially expressed genes between high and low R3HDM1 patients in each cancer type." (PMID 39376739, 2024). "Given the regulatory role of R3HDM1 expression levels in the immune response and immune cell infiltration across various human cancers from our previous analyses, we proceeded to investigate the predictive role of R3HDM1 in cancer immunotherapy." (PMID 39376739, 2024). "In fact, after expanding the sample size of normal tissues by combining the GTEx database, the estimated ROC curve indicates that R3HDM1 demonstrates satisfactory sensitivity and specificity in the diagnosis of 17 cancer types (area under the curve >0.7)." (PMID 39376739, 2024). "External validation through GEO data was conducted to assess the differential expression of R3HDM1 in different cancers." (PMID 39376739, 2024).
cancer (continued). "Interestingly, differences in R3HDM1 expression were found across various molecular subtypes of 17 cancers, including LUAD, suggesting its involvement in tumor progression and its potential for precise molecular stratification therapy and predictive value." (PMID 39376739, 2024). "The biological role of R3HDM1 in pan-cancer was explored using the GSEA method." (PMID 39376739, 2024). "This correlation may explain why patients with high levels of R3HDM1 in SKCM cancer type are prone to distant metastasis." (PMID 39376739, 2024). "Notably, R3HDM1 displayed variations across various molecular subtypes in different cancers." (PMID 39376739, 2024). "Analysis of the correlation between R3HDM1 expression and immune infiltration levels in TCGA tumor profiles using seven different algorithms revealed a significant positive association of R3HDM1 expression with B cells, CD4+T cells, CD8+T cells, and Treg cells in nearly all cancer types." (PMID 39376739, 2024). "However, the relationship between R3HDM1 of the same protein family and cancer remains unexplored." (PMID 39376739, 2024). "Additionally, we analyzed the relationship between the scores of 14 cancer-related pathways in LUAD and R3HDM1." (PMID 39376739, 2024). "Subsequently, from a pan-cancer perspective on the response to immunotherapy, we visualized the predictive capability of R3HDM1 for predicting responders and non-responders to pan-cancer immunotherapy." (PMID 39376739, 2024). "Additionally, R3HDM1 demonstrates a reverse expression pattern between T-prolif and exhausted CD8+T cells in multiple cancer tissues, suggesting its potential regulatory role in T cell function." (PMID 39376739, 2024). "Notably, in most cancer types, heightened R3HDM1 levels exhibited a negative correlation with immune cell infiltration within tumors and antigen-presenting molecule expression, contrasting with a positive correlation observed with various immune negative regulatory molecules." (PMID 39376739, 2024). "However, in most cancer types, a negative correlation was observed between high R3HDM1 levels and the recruitment of CD4+T cells (step 4), recruitment of CD8+T cells (step 4), and immune cell infiltration into tumors (step 5), further indicating the immunosuppressive role of R3HDM1 in the TME." (PMID 39376739, 2024).
metabolic disorders (1 paper, 2024). "Elaborated on the pathways and metabolic disorders mediated by R3HDM1, and identified the transcription factors regulating its expression using chip-seq." (PMID 39376739, 2024).
tumor (1 paper, 2024). "We conducted further investigation into the correlation between R3HDM1 expression and tumor staging, revealing its association with multiple tumor stages, implying a link between R3HDM1 and the progression of these tumors." (PMID 39376739, 2024). "R3HDM1, an RNA binding protein with one R3H domain, remains uncharacterized in terms of its association with tumor progression, malignant cell regulation, and the tumor immune microenvironment." (PMID 39376739, 2024). "Analyses of immune regulatory function revealed associations between R3HDM1 expression and diverse tumor immune scores, indicating a potential role for R3HDM1 in modulating the tumor microenvironment." (PMID 39376739, 2024). "To further study the cell types expressing R3HDM1 in tumor tissues, we analyzed single-cell expression levels of R3HDM1, finding widespread expression in various immune and malignant cells." (PMID 39376739, 2024). "Despite being an uncharacterized protein, the role of R3HDM1 in tumor progression, malignant cell regulation, and the tumor immune microenvironment remains largely unexplored." (PMID 39376739, 2024). "Conversely, CD4+T cells and NKT cells, pivotal in tumor eradication, showcased reduced infiltration in high R3HDM1 tumors, fostering an immunosuppressive tumor backdrop." (PMID 39376739, 2024). "Obviously, the scores related to the cell cycle are higher and positively correlated than other scores, which further confirms the sustained expression of R3HDM1 in malignant cells, indicating its involvement in tumor cell proliferation." (PMID 39376739, 2024). "Multiple immune infiltration algorithms from the TIMER2.0 database was employed to investigate the correlation between R3HDM1 expression and the tumor immune microenvironment." (PMID 39376739, 2024). "To explore potential therapeutic strategies that can inhibit the tumor-promoting effects mediated by R3HDM1, we conducted CMap analysis." (PMID 39376739, 2024). "Overall, these results strongly suggest that R3HDM1 may exhibit specific or contrasting functions across different tumor types, particularly in LUAD." (PMID 39376739, 2024). "Furthermore, exploring the relationship between R3HDM1 expression and immune modulatory molecules as well as lymphocyte subpopulation infiltration biomarkers could provide valuable insights into the role of R3HDM1 in the tumor immune microenvironment." (PMID 39376739, 2024).
R3HDM1 also shares sentences with these, for which no sentence is quoted: Bladder Urothelial Carcinoma (1 paper); non-small cell lung carcinoma (1); prostate adenocarcinoma (1); rectum adenocarcinoma (1); Skin Cutaneous Melanoma (1); Thyroid carcinoma (1).